CCL25 (C-C motif chemokine ligand 25)
Diseases named in the same sentence as CCL25 in open-access papers (continued):
Sharing a sentence is not in itself a finding about the gene and the disease.
keloid (1 paper, 2020). An irregularly shaped, elevated mark on the skin caused by deposits of excessive amounts of collagen during wound healing. "Both CCR9, the homing receptor for the small intestine and lung, and its ligand CCL25, displayed increased expression in keloid tissues (FDR ≤ 0.1)." (PMID 33329590, 2020).
knee osteoarthritis (1 paper, 2025). "CCL25 is important for MSC accumulation and knee osteoarthritis." (PMID 40503100, 2025).
lung diseases (1 paper, 2023). "The mechanisms of higher levels of mCCL6 or its homology hCCL23/CCL25 involved in the progression of lung diseases should be further investigated." (PMID 36934284, 2023).
mesothelioma (1 paper, 2025). A usually malignant and aggressive neoplasm of the mesothelium which is often associated with exposure to asbestos. "Significantly higher levels of multiple chemokines were expressed in R- vs NR- mesotheliomas, namely CCL5, CCL16, CCL17, CCL19, CCL21, CCL25, and CXCL14 Benajmini-Hochberg adjusted P values < 0.05." (PMID 40691143, 2025).
myocardial infarction (1 paper, 2021). Gross necrosis of the myocardium, as a result of interruption of the blood supply to the area, as in coronary thrombosis. "CCR9/CCL25 axis may play an important role in inflammatory cell infiltration and cardiac remodeling after myocardial infarction." (PMID 34490243, 2021).
nasal polyp (1 paper, 2025). "Increased CCL25 expression by M1 macrophages in CRSwNP might contribute to nasal polyp formation." (PMID 40894073, 2025).
ocular toxoplasmosis (1 paper, 2023). Ocular toxoplasmosis is an infection in the eye caused by the parasite, Toxoplasm a gondii. "In another study, patients with ocular toxoplasmosis displayed high levels of IFN-induced chemokines CXCL9 and CXCL10 and circulating chemokines CCL25, CCL11, CXCL12, CXCL13, and CCL2." (PMID 36755348, 2023).
oral cancer (1 paper, 2025). "Our study demonstrated that increased CCL25 levels are associated with a higher odds ratio (OR = 1.434) for oral cancer, suggesting a pro-tumorigenic effect." (PMID 40489865, 2025).
ovarian tumor (1 paper, 2010). "The effect of CCL25 on MMP expression suggests that this chemokine plays a role in ovarian tumor cell invasion via MMP modulation." (PMID 20649989, 2010).
pancreatitis (1 paper, 2024). Inflammation of the pancreas. "In parallel studies, we investigated the involvement of the interaction between CCR9 and CCL25 by assessment of pancreatitis following administration of anti-CCL25 Ab or control Ab." (PMID 39264798, 2024). "To determine whether these interactions were in fact necessary for the development of pancreatitis, we first assessed the effect of neutralizing Ab against CCL2 or CCL25 administered at the time of poly(I:C) administration." (PMID 39264798, 2024). "Thus, the proinflammatory capacity of pDCs and CXCR3+CCL25+ T cells during the mature phase of AIP is much greater than that of cDCs and CXCR3+CCL25+ T cells during the early phase of AIP, and this greater capacity translates into a greater potential to support a more robust pancreatitis." (PMID 39264798, 2024).
parasitic infection (1 paper, 2019). "In addition, the upregulation of ccl25/ccr9 was found after parasitic infection of fish." (PMID 31277329, 2019).
sarcoma (1 paper, 2018). A usually aggressive malignant neoplasm of the soft tissue or bone. "In mice, we have found tumor infiltrating T cells that express CCR9 and importantly, blockade of its ligand, CCL25, in a sarcoma model, led to increased tumor growth." (PMID 30420855, 2018). "However, we have shown that the blockade of CCL25 in a sarcoma model inoculated in immunocompetent mice was detrimental and notably, resulted in increasing the tumor growth." (PMID 30420855, 2018).
Stroke (1 paper, 2023). Sudden impairment of blood flow to a part of the brain due to occlusion or rupture of an artery to the brain. "Here, for the first time, we report that elevated CCL25 levels are associated with favorable outcome after stroke." (PMID 37794467, 2023).
type 2 diabetes (1 paper, 2024). "Furthermore, the study investigating the role of the CCL25/CCR9 axis in the pathogenesis of type 2 diabetes identified a key role of CCR9 in inducing glycose intolerance via inducing the infiltration of CD4+ T cells in the small intestine." (PMID 39411316, 2024).
tumor (61 papers, 2013 to 2026). "The CCR9-CCL25 axis also causes metastasis in the gut by directing tumor cells to intestinal sites that are rich in CCL25." (PMID 41596524, 2026). "Previously, CCL25 was found to be overexpressed in diverse cancer types and linked to increased hyperplasia and tumor aggressiveness." (PMID 38992592, 2024). "For example, TERC/CCL25 is associated with an increase in the proliferative potential of tumor cells." (PMID 36354566, 2022). "Previous studies have reported that CCL25/CCR9 is associated with tumor migration, invasion, and antiapoptosis in PC." (PMID 33195424, 2020). "CCL25 is a chemokine implicated in immune responses and tumor biology." (PMID 38992592, 2024). "In NSCLC, the CCR9/CCL25 interaction induced tumorigenesis and inhibited apoptosis of tumor cells by activating the PI3K/Akt signaling pathway." (PMID 39416786, 2024). "Animal studies further confirmed that the overexpression of hsa_circ_0000069 facilitated tumor growth in xenografted nude mice, while the inhibition of CCL25 attenuated this effect." (PMID 38992592, 2024). "To investigate the combined effects of circ_0000069 and CCL25 on tumor growth in vivo, we carried out subcutaneous injection experiments." (PMID 38992592, 2024). "CCL25, also known as thymus-expressed chemokine, is expressed in the thymus, intestinal tract and tumor cells." (PMID 39235457, 2024). "Data from previous studies have established that CCR9/CCL25 interaction promote tumor proliferation, invasion, anti-apoptosis, and migration in a variety of malignant tumors." (PMID 39416786, 2024). "The levels of cytokines CCL21, eotaxin, CXCL1, CXCL2, CCL7, CCL19, and CCL25, which are capable of supporting tumor invasion, were reduced in CM from MSCs-TRAIL by 1.2, 1.3, 4-8, 3.4-1.3, 1.5, and 1.3 times, respectively (n = 3, ** p < 0.01)." (PMID 36661524, 2023). "CXCL8/IL8, ENA-78/CXCL5, IL6, and TERC/CCL25, both in double co-culture and triple co-culture, indicated the formation of a microenvironment with chronic inflammation characteristic of the tumor stroma and the active participation of MSCs in these processes." (PMID 36354566, 2022). "Next, colony formation was used to determine the effects of different concentrations of CCL25 on tumor cells proliferation." (PMID 36003306, 2022). "HE staining showed that the density of tumor parenchymal cells in the CCL25 group was higher than that in the inhibitor groups, and tumor stroma in the CCL25 group was rarely seen." (PMID 36003306, 2022). "The in vivo data from the xenograft mouse models further proved that CCL25 administration promoted malignant tumor progression by activating the PI3K/AKT pathway." (PMID 36003306, 2022). "At the same time, TUNEL and Ki67 staining showed that compared with the PBS group, most tumor cells were in a state of proliferation and less in apoptosis in the CCL25 group." (PMID 36003306, 2022). "The effect of CCL25 on the development of SACC in vivo was examined by a xenograft tumor model in nude mice following CCL25, Vercirnon and LY294002 treatment." (PMID 36003306, 2022). "An acidity-responsive nanocarrier (NP-siCD47/CCL25) was developed to sequentially release siCD47 into cancer cells and CCL25 protein within tumor stroma." (PMID 35335881, 2022). "CC chemokine receptor 9 (CCR9), an organ-specific chemokine receptor, interacts with its exclusive ligand CCL25 to promote tumor proliferation and metastasis." (PMID 36003306, 2022). "In conclusion, targeting CCR9/CCL25 is expected to be a new approach for treating tumors, by suppressing or treating tumor patients with an autoimmune system that produces a lasting antitumor response." (PMID 34490243, 2021). "The numbers of A549 cells migrated in response to CCL25 were much more than the untreated tumor cells." (PMID 32308544, 2020). "Evidence suggests that blocking the CCR9/CCL25 axis can promote tumor progression and distant metastasis." (PMID 33299869, 2020).
tumor (continued). "Consistent with the migration assay, there were much more tumor cells invaded to the lower chamber in response to CCL25 stimulation." (PMID 32308544, 2020). "And the invasive capability of tumor cells in response to CCL25 was inhibited by CCR9 neutralization." (PMID 32308544, 2020). "CCR9 interacts with its exclusive ligand CCL25 and results in trafficking of both lymphocytes and tumor cells to participate in tumor immunity and tumor development 11, 16, 17, 27-30." (PMID 32308544, 2020). "We chose to assess the effect of co-delivering immunogen and CCL25 on anti-tumor immune responses in a model of orthotopic PDAC model." (PMID 30863398, 2019). "Collectively, these data show that CCL25 physiologically promotes anti-tumor responses in the GI system by modifying the immune microenvironment rather than by means of its chemotactic activity." (PMID 30863398, 2019). "CCR9 blockade using an antibody significantly reduced the tumor cell migration in response to CCL25 stimulation." (PMID 30420855, 2018). "For CCR9 expression in tumor cells, the data are still limited, but CCR9 expression correlates with the ability of the tumor to generate metastasis in the small intestine, the main site, in addition to the thymus, of CCL25 secretion." (PMID 29434597, 2018). "Considering chemotactic factors, the mRNA expression of CCL5, CXCL9, CXCL16, and CCL25 was higher in HCCLM3 cells from micrometastatic regions than in cells from primary tumor sites when cocultured with MSCs." (PMID 28205428, 2017). "In the past decade, chemokine ligand 25 (CCL25)/chemokine receptor 9 (CCR9) have been found in a wide variety of tumors and have been associated with tumor chemoresistance and metastasis." (PMID 26879872, 2016). "This review will examine the expression of CCR9 in cancer, recent insights into the mechanisms of CCL25/CCR9 that are involved in tumor chemoresistance and metastasis, and the potential application of CCR9-based targeted therapy." (PMID 26879872, 2016). "Researchers have shown that CCR9 that has been activated by its specific ligand CCL25 can interact with many signaling pathways, especially those involved in tumor chemoresistance and metastasis." (PMID 26879872, 2016). "CCL25 was found to be produced by all the studied tumor cell lines, although at varied levels, as determined by ELISA (Fig6A)." (PMID 25691366, 2015). "Mechanistically, data in mice and patients with cancer suggest that invigorated enterotropic cytotoxic T cells expressing the chemokine receptor CCR9 replenish the tumor microenvironment in a CCL25-mediated manner and control tumor growth, resulting in improved ICB efficacy." (PMID 41042869, 2025). "We then asked whether CCL25 expression by tumor cells could condition the extent of CCR9+ cell infiltration." (PMID 41042869, 2025). "Additionally, NAT10 was shown to inhibit CD8+ T cell accumulation near the tumor via the CCL25/CCR9 axis, fostering an immunosuppressive microenvironment." (PMID 39648231, 2024). "Moreover, the CCR9/CCL25 chemokine axis plays an important role in shaping TME by attracting immune cells in the tumor, leading TME toward an immunosuppressive state." (PMID 39416786, 2024). "Interestingly, previous studies have shown that this chemokine is not expressed in human or murine TNBC and that intratumoral delivery of CCL25 enhances anti-tumor effects by stimulating CCR9 + CD8 + T cell tumor infiltration." (PMID 37505292, 2023). "Interestingly, CCR9-expressing T cells have been shown to contribute to anti-tumor immunity, and their recruitment into the tumor-bed (by CCL25 intratumoral delivery) improves immunotherapy efficacy." (PMID 36875124, 2023). "Then, we focused on the tumor cell and lymphocyte interactions mediated by chemokines and demonstrated that mTEC-like and mcTEC-like tumor cells in TETs could induce DP cell migration for positive selection through CCL25:CCR9 and CXCL12:CXCR3 interactions." (PMID 36115836, 2022).
tumor (continued). "In addition, the JAK/STAT pathway activated by CCL25 can alleviate the antitumor ability of T cells and promote the immune escape of tumor cells." (PMID 36003306, 2022). "Next, using living and dead cell experiment, we further verified whether CCL25/CCR9 promoted the growth of tumor cells through activating AKT signaling pathway." (PMID 36003306, 2022). "However, CCL25 is not expressed on TNBC cells; therefore, it was proposed to intratumorally deliver CCL25 into a murine TNBC model in order to increase CCR9+CD8+ T-cell infiltration in the tumor." (PMID 35335881, 2022). "CCL25 can also recruit MDSC into the tumor microenvironment." (PMID 34961815, 2021). "The combination treatment caused increased secretion of CCL2, CCL21, CXCL1, CXCL2, CXCL5, CXCL9 and CXCL16, whereas the levels of CCL11, CCL17, CCL19, CCL22, CCL25, CCL27 and CX3CL1, which are associated with protumourigenic effects, were decreased in the tumours." (PMID 33014356, 2020). "Tumor growth was significantly reduced in mice previously immunized in the presence of CCL25." (PMID 30863398, 2019). "Moreover, in this tumor model, high levels of CCL25 were found in the tumor microenvironment and these levels were much higher than the levels found in the gut providing a possible explanation for the recruitment of these CCR9+ T cells to the tumor bed." (PMID 30420855, 2018). "Whether cultured alone or cocultured with MSCs, HCCLM3 cells from micrometastatic regions expressed higher levels of CCL25 than HCCLM3 cells from primary tumor sites." (PMID 28205428, 2017). "Therefore, the mechanisms of CCL25/CCR9-induced tumor metastasis are complex and require further research." (PMID 26879872, 2016). "Therefore, in this review, we focus on CCR9 as a potential tumor biomarker and on how the CCL25/CCR9 pathway is involved in tumor chemoresistance and metastasis." (PMID 26879872, 2016). "In the same line, the chemokines CCL2 or CCL25 produced by cancer cells could be attractant for MSCs and explain their tropism for tumor sites." (PMID 26362269, 2015). "Likewise, interferon response genes (including TLR3, MX1, RSAD2, IFI44, IFI27, IFIT1, and IFIT3), and chemokine genes (including CCL7, CXCL10, CXCR1, and CCL25) were significantly increased in PM-treated MM tumor tissues, whereas panobinostat showed minimal effects at equivalent doses." (PMID 40562746, 2025). "This review highlights chemokine-mediated mechanisms, focusing on CCR9/CCL25 and CXCL12/CXCR4 axes, which promote tumor growth, metastasis, and immune evasion via PI3K/AKT and MAPK signaling." (PMID 40607416, 2025). "In vitro, CCL25 enhances CD4+; T cell migration, suggesting a dual role for this axis in both tumor progression and immune surveillance." (PMID 40607416, 2025). "ELISA and flow cytometry confirmed that NAT10 knockdown significantly increased CCL25 levels, promoting CD8+ T cell recruitment and enhanced cytotoxicity in the tumor microenvironment." (PMID 39648231, 2024). "On the other hand, CCR9 is the unique receptor of CCL25, a chemokine whose expression increased in our 4T1 CSF1−/− tumor cell line." (PMID 37505292, 2023). "The interaction of CCL25 and CCR9 promotes tumor growth and metastasis in SACC by activating the PI3K/AKT signaling pathway, offering a promising strategy for SACC treatment." (PMID 36003306, 2022). "CCR9/CCL25 can also activate Ras/Raf/MARK and RhoA/Rock signals to strengthen the degradation of ECM and change the cytoskeleton arrangement, thus enhancing tumor cell motility (Golec, Henao Caviedes & Baldwin, 2016)." (PMID 36003306, 2022). "Immature DCs can be recruited into the TME, attracted by tumor-secreted factors such as CCL2, CCL20/MIP3a, CCL25, CCL5, CXCL12, CXCL1, and CXCL5, while mature DCs reside in areas surrounding the tumor." (PMID 35267487, 2022). "Tumor expression or serum concentrations of CCL5, CCL25, or PD-L1 were determined with immunohistochemistry or ELISA." (PMID 34771505, 2021).